TCF20 (transcription factor 20)
Description:
Transcriptional activator that binds to the regulatory region of MMP3 and thereby controls stromelysin expression. It stimulates the activity of various transcriptional activators such as JUN, SP1, PAX6 and ETS1, suggesting a function as a coactivator.
Synonyms: TCF-20; SPBP; AR1; DDVIBA
Tractability: PROTAC: UniProt records ubiquitination sites on it; ubiquitination databases record sites on it; its protein half-life has been measured.
Gene: Protein-coding gene on chromosome 22 (42,160,013 to 42,343,616, reverse strand). Ensembl gene ENSG00000100207.
Subcellular location: Nucleus
Subcellular location (Human Protein Atlas): Nucleoplasm; Nuclear bodies
Gene Ontology:
Molecular function: protein binding; RNA binding; transcription coactivator activity
Biological process: positive regulation of transcription by RNA polymerase II
Cellular component: nuclear body; nucleoplasm; nucleus
Genetic constraint (gnomAD): Loss-of-function variants: 3 observed, 155.16 expected, observed/expected ratio (o/e) 0.0193, 90% interval 0.008 to 0.05. The upper end of that interval is the gene's LOEUF score, 0.05, which puts it in group 1 of 6, group 1 being the genes least tolerant of losing a copy. Missense variants: 2,350 observed, 2,560 expected, observed/expected ratio (o/e) 0.92, 90% interval 0.89 to 0.95. Synonymous variants: 1,049 observed, 960.51 expected, observed/expected ratio (o/e) 1.09, 90% interval 1.04 to 1.15.
Gene-disease validity (ClinGen):
ClinGen rates the evidence that TCF20 causes each of these diseases.
developmental delay with variable intellectual impairment and behavioral abnormalities (autosomal dominant): Definitive. A neurodevelopmental disorder caused by a mutation in TCF gene, characterized by impaired intellectual development with speech difficulties and behavioral abnormalities, most commonly autism spectrum disorder (ASD), defects in attention, and/or hyperactivity.
Homologues: Orthologues: chimpanzee TCF20 (99% identical), macaque TCF20 (97% identical), dog TCF20 (94% identical), rabbit TCF20 (93% identical), mouse Tcf20 (93% identical), pig TCF20 (92% identical), guinea pig TCF20 (92% identical), rat Tcf20 (92% identical), tropical clawed frog tcf20 (54% identical), zebrafish tcf20 (28% identical), mouse Zfp957 (17% identical), Drosophila melanogaster CG5098 (11% identical). Paralogues in human: RAI1 (23% identical).
Diseases named in the same sentence as TCF20 in open-access papers:
TCF20 is named in the same sentence as 68 diseases in open-access papers, as found by Europe PMC text mining. Sharing a sentence is not in itself a finding about the gene and the disease. The quoted sentences say what the papers report.
Intellectual disability (7 papers, 2014 to 2025). "In humans, variants in the TCF20 gene can result in developmental and intellectual disability, autism, dysmorphisms, and neurological features, alongside various other impairments spanning gastrointestinal issues, hepatic issues, and skeletomuscular systems." (PMID 40011607, 2025). "Individually, de novo nonsense and frameshift variants of TCF20 have been reported in individuals with intellectual disability and postnatal overgrowth." (PMID 38043798, 2024). "The BRWD3 gene (MIM 300553), located at Xq21.1, is associated with X-linked mental retardation and macrocephaly, while TCF20 (MIM *603107) variants with intellectual disability and postnatal overgrowth." (PMID 36833222, 2023). "Through exome sequencing in another project, we independently identified a de novo frameshifting mutation of TCF20 in a woman with ASD and moderate intellectual disability." (PMID 25228304, 2014). "For example, phosphosites on CDK13, TCF20 and NONO, genes that are known to be strongly associated with intellectual disability, exhibit varying temporal profiles (Sup." (PMID 39282277, 2024).
breast cancer (6 papers, 2008 to 2019). A primary or metastatic malignant neoplasm involving the breast. "MCF-7 human breast carcinoma cell line is estrogen receptor (ER) positive; thus, the expression of TCF20 should inhibit ER and consequently impair the viability of the tumor cells." (PMID 28458685, 2017). "In the current study, we used MCF-7 breast cancer cell line to determine the effect of EFA-CLA, as potential ligands for peroxisome proliferator-activated receptors (PPARs), on identified in silico PPAR-responsive genes: BCAR3, TCF20, WT1, ZNF621, and THRB (transcript TRβ2)." (PMID 28458685, 2017).
intellectual impairment (5 papers, 2020 to 2025). "Pathogenic variants in the TCF20 gene have been identified in over 100 patients and are associated with autosomal dominant developmental delay with cognitive impairment and behavioral abnormalities (TCF20-NDD)." (PMID 41300659, 2025). "Notably, a combined approach using WES and array-CGH in 31 unrelated families with an SMS-like phenotype identified pathogenic variants in TCF20, defining a new syndrome termed developmental delay with variable intellectual impairment and behavioral abnormalities (DDVIBA, OMIM #618430)." (PMID 35205380, 2022).
developmental delay (4 papers, 2019 to 2025). "In addition, pathogenic variants in TCF20 have also been observed in two large cohort studies with cognitive phenotypes of ID and developmental delay (DD)." (PMID 30819258, 2019). "Autosomal dominant variants in transcription factor 20 (TCF20) can result in TCF20-associated neurodevelopmental disorder (TAND), a condition characterized by developmental delay and intellectual disability, autism, dysmorphisms, dystonia, and variable other neurological features." (PMID 40011607, 2025).
Ataxia (3 papers, 2019 to 2025). Ataxia refers to impaired coordination of voluntary muscle movement. "Over 100 patients have been identified with mutations in TCF20, and their clinical features include developmental delay, ID, autism, ataxia, hypotonia, craniofacial dysmorphisms, and seizures." (PMID 39766920, 2024). "Some patients with TCF20 mutations exhibit phenotypic features reminiscent of SMS, including craniofacial abnormalities, neurological disturbance, seizure, ataxia, abnormal gait, failure to thrive, food-seeking behaviors, and sleep disturbances." (PMID 39766920, 2024).
autism (3 papers, 2014 to 2025). Persistent deficits in social interaction and communication and interaction as well as a markedly restricted repertoire of activity and interest as well as repetitive patterns of behavior. "Intriguingly, TCF20 was one of the highest ranking candidate autism risk genes (category 2) according to the most recent version of the SFARI Gene resource." (PMID 33133139, 2020). "Open reading frames and intron/exon boundaries of the two physically disrupted genes identified, TCF20 and TNRC6B, were sequenced in 342 families (260 multiplex and 82 simplex) ascertained by the International Molecular Genetic Study of Autism Consortium (IMGSAC)." (PMID 25228304, 2014).
Anxiety (2 papers, 2023 to 2024). Intense feelings of nervousness, tension, or panic often arise in response to interpersonal stresses. "Moreover, TCF20 can also act on estrogen (ER) and androgen (AR) receptors to play a role in circadian rhythm, and changes in TCF20 activity may be linked with sleep disorder, hyperactivity, anxiety, obsessive-compulsive disorder, and overgrowth, etc." (PMID 37303953, 2023).
schizophrenia (2 papers, 2020 to 2023). A major psychotic disorder characterized by abnormalities in the perception or expression of reality. "Mutations in TCF20 were also implicated in Phelan-McDermid syndrome, developmental disorders, and schizophrenia." (PMID 33133139, 2020).
sleep disorder (2 papers, 2019 to 2023). A change from the patient's baseline sleeping pattern, in the hours slept and/or an alteration/dysfunction in the stages of sleep. "Phenotypes specific for TCF20, such as sleep disturbances and movement disorders, may help clinically distinguish the 22q13.2 deletions from the 22q13.3 deletions (SHANK3)." (PMID 30819258, 2019).
-dependent (1 paper, 2017). "First one TCF20 can act as a phosphoserine-specific repressor of estrogen receptors (ER) in estrogen-dependent tumors." (PMID 28458685, 2017).
autoimmune hepatitis (1 paper, 2023). Hepatitis caused by autoantibodies. "It was also reported that loss of TCF20 function might lead to immune system diseases, such as autoimmune hepatitis and hyper-IgE." (PMID 37303953, 2023).
craniosynostosis (1 paper, 2014). Craniosynostosis is defined as the premature fusion of one or more cranial sutures leading to secondary distortion of skull shape resulting in skull deformities with a variable presentation. "Exome sequencing of family #6 revealed a heterozygous mononucleotide frameshifting mutation of TCF20 in a woman with craniosynostosis, a phenotype that was also present in her mother." (PMID 25228304, 2014). "The final piece of evidence linking TCF20 with ASD came serendipitously, while studying the genomic origins of craniosynostosis in an unrelated study." (PMID 25228304, 2014).
desmoid tumor (1 paper, 2018). A desmoid tumor (DT) is a benign, locally invasive soft tissue tumor associated with a high recurrence rate but with no metastatic potential. "Moreover, TCF20 expression can distinguish desmoid tumors from nodular fasciitis." (PMID 29467924, 2018).
dyspraxia (1 paper, 2025). "We describe a case with neurodevelopmental disorder, severe dyspraxia, and a novel pathogenic variant in the TCF20 gene." (PMID 41300659, 2025).
kidney cancer (1 paper, 2015). Primary or metastatic malignant neoplasm involving the kidney. "Thus, the changes we identified in alternative splicing of these genes are appealing potential diagnostic markers for tumor initiation in several cancers, and FBLN2, AP2B1 and TCF20 are also good prognostic markers for patient survival in breast, lung, and kidney cancers, respectively." (PMID 25908786, 2015).
lung adenocarcinoma (1 paper, 2018). A carcinoma that arises from the lung and is characterized by the presence of malignant glandular epithelial cells. "TCF20 is involved small cell lung cancer (SCLC) and advanced lung adenocarcinomas carcinogenesis and chemoresistance." (PMID 29467924, 2018).
muscular dystrophy (1 paper, 2021). Muscular dystrophy (MD) refers to a group of more than 30 genetic diseases characterized by progressive weakness and degeneration of the skeletal muscles that control movement. "The total cohort GWA for udder depth associated a novel SNP at BTA 5:113268242 located within an intron of Transcription Factor 20 (TCF20), which has been associated with human muscular dystrophy and postnatal overgrowth, such as tall stature, macrocephaly, and obesity." (PMID 33920522, 2021).
Smith-Magenis syndrome (1 paper, 2019). Smith-Magenis syndrome (SMS) is a complex genetic disorder characterized by variable intellectual deficit, sleep disturbance, craniofacial and skeletal anomalies, psychiatric disorders, and speech and motor delay. "A recent study by Liu and colleagues identified mutations in TCF20, a paralog of RAI1, among individuals manifesting a novel syndrome that has phenotypes similar to those of Smith-Magenis syndrome (a disorder caused by disruption of RAI1)." (PMID 31014384, 2019).
Wiedemann-Steiner syndrome (1 paper, 2022). Wiedemann-Steiner syndrome is a rare genetic condition characterized by distinctive facial features, hairy elbows, short stature, and intellectual disability. "The biological relevance of these proteins is highlighted by the clinical consequences of their haploinsufficiency, as KMT2A and TCF20 are the causative genes of Wiedemann-Steiner syndrome (WDSTS, OMIM #605130) and of a syndromic neurodevelopmental disorder (OMIM #618430), respectively." (PMID 35205380, 2022).
tumor (13 papers, 2009 to 2025). "As TCF20 shows extensive sequence identity to a mouse transcription factor which activates the expression of the stromelysin-1 mRNA for tumor invasion and metastasis, therefore we will examine whether this function will be performed by TCF20 protein in human CRC cell lines." (PMID 29467924, 2018). "However the roles of VEGF-A, CHD4 and TCF20 genes in CK20-related micrometastasis are unknown, the expression of them in LNs from Tumor-Node-Metastasis (TNM) stage III and IV CRC patients would be studied in order to know whether this micrometastasis pathway is preserved in metastatic LNs." (PMID 29467924, 2018).
neurodevelopmental disorder (8 papers, 2019 to 2025). A behavioral and cognitive disorder with onset during the developmental period that involves impaired or aberrant development of intellectual, motor, or social functions. "This case report is only the second confirmed case with physical evidence of germline mosaicism in TCF20-associated neurodevelopmental disorders and the first to confirm the inheritance of the same TCF20 variant in siblings." (PMID 40011607, 2025). "Autosomal dominant variants with a parent affected with significant neurodevelopmental disorder were identified in two families (TCF20, paternally inherited, and RERE, maternally inherited)." (PMID 38256266, 2024). "TCF20, a transcriptional coactivator associated with neurodevelopmental disorders, displayed two distinct patterns with respect to its detected phosphosites." (PMID 39282277, 2024). "Germline mosaic variants may represent a clinically salient yet under-detected mode of disorder-associated inheritance not only in TCF20-associated disorder, but other neurodevelopmental disorders as well." (PMID 40011607, 2025). "However, dysmorphisms, neurological findings, hepatic issues, and other organ system-specific impairments appear to be variable among cases, highlighting the morphological heterogeneity of TCF20-associated neurodevelopmental disorder." (PMID 40011607, 2025). "Considering the diagnosis of neurodevelopmental disorders related to TCF20, it would be more appropriate to refer to it as a co-occurring developmental coordination disorder (co-occurring DCD)." (PMID 41300659, 2025). "Pathogenic variants in TCF20 act in an autosomal dominant mode (MIM 618430; Orphanet 35099) and result in TCF20-associated neurodevelopmental disorders (TAND)." (PMID 40011607, 2025). "TCF20 is another transcription factor whose mutations lead to ASD and TCF20-associated neurodevelopmental disorders." (PMID 39766920, 2024). "Also, we have identified 15 de novo variants in genes that were previously implicated in ASD or related neurodevelopmental disorders (PHF21A, WASF1, TCF20, DEAF1, MED13, CREBBP, KDM6B,SMURF1, ADNP, CACNA1G, MYT1L, KIF13B, GRIA2, CHM, and KCNK9)." (PMID 38572415, 2024).
cancer (3 papers, 2011 to 2015). A tumor composed of atypical neoplastic, often pleomorphic cells that invade other tissues. "Taken together, it is likely that splicing changes in FN1, FBLN2, AP2B1 and TCF20 are also drivers of cancer initiation and progression, which still needs to be determined functionally." (PMID 25908786, 2015). "A statistically significant correlation was observed for AP2B1, TCF20 and FBLN2 in one or two of the cancer types examined." (PMID 25908786, 2015). "Some of the common cancer-regulated alternative splicing events we identified in genes such as FN1, FBLN2, AP2B1 and TCF20 are most likely oncogenic drivers." (PMID 25908786, 2015).
psychiatric disorder (2 papers, 2020 to 2024). A disorder characterized by behavioral and/or psychological abnormalities, often accompanied by physical symptoms. "We identified 7 genes (Cap2, Shc3, Lrrc7, Rims2, Cntnap2, Tcf20, and Trank1) associated with neurodevelopmental and psychiatric disorders that feature social impairments." (PMID 38263132, 2024).
immune disorders (1 paper, 2023). "The patient in this report carried a pathogenic variation in the TCF20 and then developed rare immune system disorders." (PMID 37303953, 2023). "Presently, the specific mechanism by which TCF20 variation induces immune system diseases has not yet been reported." (PMID 37303953, 2023).
TCF20 also shares sentences with these, for which no sentence is quoted: prostate carcinoma (5 papers); epilepsy (4); Dystonia (3); infection (3); autism spectrum disorder (2); breast adenocarcinoma (2); kidney disease (2); asthma (1); bacterial infection (1); bladder cancer (1); cardiac hypertrophy (1); cervical carcinoma (1); chronic lung infections (1); colon cancers (1); colorectal carcinoma (1); cystic kidneys (1); depression (1); diabetes (1); Failure to thrive (1); frontotemporal dementia (1); gastric cancer (1); generalized anxiety disorder (1); glioma (1); Hepatitis (1); Hypertension (1); leukemia (1); lung carcinoma (1); Macrocephaly (1); melanoma (1); meningioma (1).
A further 14 diseases each share a sentence with TCF20 in 1 paper.